IL5 (interleukin 5)
Diseases named in the same sentence as IL5 in open-access papers (continued):
Sharing a sentence is not in itself a finding about the gene and the disease.
asthma (continued). "Another study reported that treatment with a humanized anti-IL-5 monoclonal antibody called mepolizumab (MEP) can attenuate allergen-induced Th2 inflammation and tissue remodeling by downregulating Chi3l1 levels in asthma patients." (PMID 39769202, 2024). "Type 2-high and type 2-ultra-high asthma again involve IL-4, IL-5, and IL-13, while type 2-low asthma, due to the lack of biomarkers, is described as a type with different mechanisms of disease, including IL-1β, IL-6, or neutrophil infiltration." (PMID 38785919, 2024). "There are other experimental studies on BALF cytology and cytokine response (IL-4, Il-5, IL-13, IL-17 and IFN-γ) in animals only with individual exposure to OVA in OVA-induced asthma; the impact of anti-Il-17 or dexamethasone treatment alone in this model was evaluated." (PMID 38543124, 2024). "Concerning the involvement of IL-5, present in upper airways, and the local response to SARS-CoV-2 infection, in a general way, studies have been focusing on patients with some diseases in the airways, mainly asthma and allergies." (PMID 38273281, 2024). "Interestingly, the expression of miR-181a in the lung of allergic rhinitis mice reduced the count of eosinophils in BALF and decreased IL-4, IL-5, and IL-13 by targeting high mobility group box 1 (HMGB1), resulting in retarded development of asthma." (PMID 38337625, 2024). "Furthermore, compared to the Asthma + oe-NC + IDF-11,774 group, the Asthma + oe-MDM2 + IDF-11,774 group demonstrated a significant increase in IL-4, IL-5, IL-13, and IgE levels." (PMID 39061007, 2024). "Moreover, connections between IL-5 and AREG have been reported in the severe asthma and lung fibrosis." (PMID 38831884, 2024). "There is evidence that treatment of allergic asthmatics with inhaled steroids was able to reverse the high levels of IL-5, IL-13 and IL-9 produced by ILC2s via STAT3, STAT5, STAT6, JAK3 and MEK signaling pathways, which was accompanied by better asthma control." (PMID 39452061, 2024). "Additionally, we examined the levels of inflammatory cytokines in sputum and found that IL‐5, IL‐6, IL‐8, TNF‐α, IFN‐γ, CCL17, CCL22, CXCL10, CCL4, CCL2, IL‐4, IL‐13, and CCL26 were significantly lower in stable asthma than in acute asthma." (PMID 39508721, 2024). "Clustering patients suggest asthma, N-ERD, allergy, eosinophil count and IL-5 could have a role in predicting recurrence and severe disease." (PMID 38913122, 2024). "In addition, treatment with tectochrysin or dexamethasone significantly reduced the levels of IL-4 and IL-5 as well as the IL-4/IFN-γ ratio in BALF of asthmatic mice, indicating the potential of tectochrysin as a therapeutic agent for asthma." (PMID 39759448, 2024). "The authors proposed that a combined model comprised of eosinophil cationic protein, IL-5, pre-ESS MLM score, asthma, and anti-double-stranded DNA IgG could accurately predict polyp recurrence." (PMID 39328679, 2024). "In addition, it significantly attenuated the symptoms of asthma attacks, reduced the number of macrophages, lymphocytes, neutrophils, and eosinophils in BALF and inflammatory cytokines, including IL-1β, IL-5, IL-6, and IL-13." (PMID 38579176, 2024). "The results of the MR analysis showed that asthma increased the levels of IL-5 and IL-9, but did not affect levels of other cytokines." (PMID 39175819, 2024). "Notably, Th2 cell-related cytokines such as IL-4, IL-5, and IL-13 and Th17 cell-related cytokines such as IL-6 and TNF-α increase in patients with asthma." (PMID 37569846, 2023). "Several cytokines, including interleukin (IL)-4, IL-5, IL-13, IL-25, and IL-33, thymic stromal lymphopoietin (TSLP), and cells such as innate lymphoid cells type 2 (ILC2s), play crucial roles in orchestrating the inflammatory response in asthma." (PMID 37765327, 2023).
asthma (continued). "T2 high asthma is characterized by reduced lung function, poor asthma control, increased IgE levels, increased responsiveness to ICS treatment and persistent eosinophilic inflammation mediated by cytokines such as IL-4, IL-5 and IL-13." (PMID 40980110, 2023). "We compare peripheral blood (PB) isolated ILC2's proliferative capacity, IL‐5 and IL‐13 secretion and phenotype between healthy without asthma (HC), non‐asthma allergic (NAA), mild asthma (MA) and severe allergic and eosinophilic asthma (SA) subjects." (PMID 37114915, 2023). "As well, this circumstance also has been described in asthma patients, where some interleukins have been found raised, such as IL6, IL-4, IL-5, and IL-13, secreted from CD4+ lymphocytes, promoting an allergic inflammation which involves a worse prognosis of asthma disease." (PMID 37920579, 2023). "Five monoclonal antibodies (mAb) targeting some molecules participating in type 2 (T2) inflammation (i.e., anti-IL4/13, anti-IL-5, anti-IL-5Rα, anti-IgE, anti-thymic stromal lymphopoietin (TSLP)) are now available for severe asthma and some of them are also indicated for CRSwNP." (PMID 37108417, 2023). "A basic science study has shown that patients with asthma have more blood ILC2s which produce more IL-5 and IL-13 than healthy controls, indicating that the evaluation of blood ILC2 in patients with asthma might be clinically useful." (PMID 36941691, 2023). "High serum periostin, TNFα, IL-4, IL-5, and the chitinase-like protein YKL-40 levels, as well as low serum IL-37 levels, were associated with exacerbated asthma in nonsmokers." (PMID 37367073, 2023). "In this study, anti-IL-5/IL-5Rα mAbs decreased the frequency of exacerbation, reduced the dose of oral corticosteroids, and improved lung function in patients with ABPA complicated by asthma, even in those refractory to omalizumab." (PMID 37015988, 2023). "This might have important implications for patient selection and effectiveness of biologic therapies used in severe asthma in EMG, such as anti‐IgE therapy (omalizumab) and anti‐interleukin (IL)‐5 agents." (PMID 37876034, 2023). "Regarding the evaluation of inflammatory markers in the airways, we observed that the ACO group, compared to the asthma model (OVA), was higher in cells for IL-1β, IL-10, IL-17, and IFN-γ, with the exception of IL-5 positive cells that were superior in the OVA group." (PMID 37511021, 2023). "Although 30 mg/kg of CCE exhibited the declines of asthma factors such as inflammatory cell count and IL-5, other factors did not observe the significant difference in IL-4, IL-13, OVA-specific IgE, histological analysis and protein expression." (PMID 36034804, 2022). "In polyp samples containing SEA-specific IgE antibodies, severe eosinophilic inflammation, manifested by the upregulation of IL-5, eosinophil chemokines, eosinophil cationic protein (ECP), and caspase-leukotriene synthesis, was observed, thus contributing to the severity of asthma." (PMID 35878202, 2022). "Other factors were explored to predict the clinical response to anti-IL-5 mAb (N-ERD, previous surgery, sex, smoking habit, comorbid conditions: emphysema, bronchiectasis, sleep apnea, asthma, gastroesophageal reflux, diabetes, hypercholesterolemia and/or hypertension)." (PMID 36498632, 2022). "The results of the cytokine contents do not agree with the higher levels of IL-4, IL-5 and IL-13 reported in other asthma models." (PMID 35276769, 2022). "One study reported that IL-5-stimulated blood eosinophils reduced EDN degranulation in older patients with asthma compared to younger patients, while they spontaneously released equal EDN in older patients with asthma between in the older and the younger ones." (PMID 36291665, 2022). "It is important to note however, that these anti-IL-5 treatments are not a sole solution to asthma, rather they have been approved as an add-on therapy for patients already taking high dosage corticosteroids." (PMID 36232470, 2022).
asthma (continued). "In conclusion, our study shows that bergenin regulates the NF-κB pathway and blocks p65 translocation into the nucleus by activating SIRT1, thereby reducing the release of proinflammatory factors (such as IL-1β, IL-5, IL-6, and MMP-9 by macrophages) to play a role in asthma treatment." (PMID 36313381, 2022). "Notably, latent Chlamydia pneumoniae and Mycoplasma pneumoniae infections have been reported to contribute to the pathogenesis of asthma, showing an increase in IgE, IL-4, IL-5, IL-8, and IFN-γ in asthma." (PMID 36291665, 2022). "In summary, this study demonstrated that the RSV NS1 could regulate inflammatory factors, such as LTB4 and IL-5 through the miR-19a-3p and 5-LO pathway, which provided insights into the molecular mechanism of RSV in mediating asthma or recurrent wheezing." (PMID 35637792, 2022). "Moreover, SPC treatment improved lung tissue pathology, reduced the cytokine production in BALF (IL-4, IL-5, and IFN-γ), and regulated Th1/Th2 immune imbalance in an asthma model." (PMID 35631330, 2022). "And, what is inconsistent with our expectation is that the content of chemokines rather than Th2 cytokines (IL-4, IL-5, IL-13, etc.)surged in the asthma model group, which indicates that the chemokines count for the pathological process of asthma." (PMID 35600943, 2022). "Furthermore, it was found that the levels of TNF-α, IL-1β, IL-4, IL-5, and IL-13 in the BALF, and the levels of IL-17, IL-6, and OVA-specific IgE were observably increased in serum of RSV-infected asthma mice, while the level of IFN-γ was decreased." (PMID 36213326, 2022). "No targeted biologics were used by the Asthma group (anti-IgE, anti-interleukin (IL) 4 or anti-IL5)." (PMID 35963877, 2022). "In line with plasma IL-4 and IL-25 data, patients with asthma comorbid AR had higher levels of IL-5 (6.94 [5.74, 10.69]) than those without asthma (4.07 pg/ml [3.61, 4.72] pg/ml, P < 0.001)." (PMID 35348596, 2022). "IL-5-anchored CCAR-T cells exhibited selective and effective killing capacity in vitro and restricted eosinophil differentiation with apparent protection against allergic airway inflammation in two mouse models of asthma." (PMID 35973984, 2022). "Interestingly, lncRNAs also regulated the expression of cytokines (IL-5 and IL-13), transcription factors (STAT5 and STAT6) and chemokines (CCL17 and CCL22), which mediated Th1 and Th2 inflammatory response in asthma." (PMID 35656293, 2022). "Cytokines, e.g. TNF, IL1β, IL5, IL6, IL12 and IL23, represent important therapeutic targets in immune-mediated inflammatory diseases (IMIDs), such as inflammatory bowel disease (IBD), psoriasis, asthma, rheumatoid and juvenile arthritis." (PMID 35731827, 2022). "Immunomodulators such as anti-immunoglobulin E (IgE), anti-IL5, and anti-IL4 Ra antibodies have shown potential benefits in improving asthma control and reducing acute exacerbation in patients with severe asthma; however, each molecular-targeted medicine is limited to a specific genotype." (PMID 36345503, 2022). "Expression of the cytokines TNF-α, IL-1β, IL-6, IL-5, and IL-8 were increased in placentae of female, but not male fetus, in pregnancies complicated by asthma." (PMID 36046194, 2022). "Meanwhile, according to the “Disease relevance analysis” function of POPPIT, we found that the alpha subunit of interleukin-5 receptor is related to asthma (distance = 1) by its direct interaction with interleukin-5 (gene name: IL5), which is known to play a role in the etiology of asthma." (PMID 35338014, 2022). "In addition, the concentrations of IL-4, IL-5, and IL-13, as well as IL-1β, IL-6, and TNF-α, were greatly elevated in BALF and lung tissues, especially in lung tissues, of asthma mice, which were suppressed after the treatment of Ferr-1 and/or 3-MA." (PMID 35154576, 2022). "Our study results revealed that IL-5 and GM-CSF, but not IL-3, exhibited a significant effect on the proliferative properties of eosinophil subtypes in asthma patients." (PMID 36497064, 2022).
asthma (continued). "Comparison of anti-IL-5 between eosinophilic COPD and asthma." (PMID 34795588, 2021). "Th2 cytokines (such as interleukin (IL)-4, IL-5, and IL-13) are produced by CD4+ T cells and are believed to play a key role in asthma pathogenesis by promoting recruitment and activation of mast cells and eosinophils, which are the primary effector cells in the allergic response." (PMID 34356851, 2021). "Th2 cytokines, especially IL-5 and IL-13, are decreased by miR-146a on ILC2 by inhibiting IRAK1, and miR-146a also alters neutrophil migration from bronchial epithelial cells in asthma." (PMID 34566492, 2021). "It was shown that Th2 cytokines, such as IL-4, IL-5, and IL-13, together with eotaxin/CCL11, regulate critical aspects of eosinophil recruitment, allergic inflammation, and airway hyperresponsiveness in asthma." (PMID 33806927, 2021). "The Global Initiative for Asthma (GINA) has highlighted corticosteroids and biological therapies (e.g., anti-IgE antibody, anti-interleukin-5/5Rα, and anti-interleukin-4Rα) in their guidelines for asthma treatment; however, these treatments primarily target Th2-mediated airway inflammation." (PMID 33975625, 2021). "Although studies have suggested benralizumab as a promising biologic for asthma exacerbations, the clinical efficacy of benralizumab as compared to other IL-5 targeted therapies has not been established." (PMID 33917396, 2021). "ILC2s do not depend on T cells and secrete a large number of type 2 cytokines (such as IL-4, IL5, IL-9, and IL-13) under the function of IL-25, IL-33 and thymic stromal lymphopoietin (TSLP) to participate in asthma, virus infection and worm-host defense related with the type 2 immune response." (PMID 33514798, 2021). "In the present study, we documented immunomodulatory mechanisms of GSYJ that relieve asthma symptoms, including AHR, lung inflammatory cell infiltration, and increased serum total IgE levels by regulating the expression of IL-5, IL-6, IFN-γ, IL-12, IL-1β, RANTES, and iNOS." (PMID 33708257, 2021). "Collectively, there are numerous immune cells, outside of eosinophils, which can contribute to inflammatory processes inherent in severe asthma, independent of IL-5." (PMID 35126131, 2021). "Furthermore, CXCR4 was reported to decrease airway responsiveness and inflammation by reducing the levels of IL-4, IL-5, and IL-13 in the BALF in OVA-induced asthma." (PMID 34118928, 2021). "In mice models of asthma, isoquercitrin or quercetin, reduced eosinophil counts in the bronchoalveolar lavage fluid (BALF), blood and lung parenchyma, neutrophil counts in blood but only isoquercitrin reduced IL-5 levels in lung homogenate." (PMID 34567150, 2021). "mRNA expression levels of IL4, IL5, and IL13 are increased in sputum cells from asthmatic patients in comparison to controls and can be used as molecular biomarkers to categorize patients into T2-high and T2-low asthma endotypes similarly." (PMID 33513844, 2021). "Other studies have illustrated that deficiency of HIF-1α can reduce eosinophil infiltration, goblet cell hyperplasia, and levels of cytokines IL-4, IL-5, and IL-13 in the lungs of OVA-induced asthma models, further highlighting the importance of the elevated levels of HIF-1α in asthma." (PMID 33980319, 2021). "Meanwhile, Pts treatment could reduce IL‐4, IL‐13, IL‐5, and IgE (total and OVA specific) levels in the asthma model mice." (PMID 34342160, 2021). "Wild-type DC10 ablated the OVA-asthma phenotype via induction of Foxp3+ Treg responses, but CD40-/- DC10 had no discernible effects on primary facets of the phenotype (e.g., IL-5, IL-9, IL-13 levels, IgE & IgG1 antibodies; p>0.05) and were ≤40% effective in reversal of others." (PMID 33793599, 2021). "In T2-high asthma, CD4+T helper 2 (Th2) cells and innate lymphoid cells group 2 (ILC2), eosinophils, immunoglobulin E (IgE) and T2 cytokines such as interleukin (IL)-4, IL-5 and IL-13 contribute to its pathogenesis." (PMID 34777398, 2021).
asthma (continued). "To enrich our study, we compared the efficacy of anti-IL-5 therapy in eosinophilic COPD and asthma." (PMID 34795588, 2021). "In conclusion, we established an acute model of asthma with AHR, airway inflammation, and increasing levels of IL-4 and IL-5, which could be effectively reduced by the treatment of HL Granule." (PMID 33967801, 2021). "This study aimed to determine whether induced sputum samples can be used for gene expression profiling of T2-high asthma classified by IL4, IL5, and IL13 expression." (PMID 33513844, 2021). "BAMBI knock out mice model of asthma demonstrated significantly reduced airway hyperresponsiveness, pulmonary inflammation, broncho-alveolar lavage fluid (BALF) eosinophil count, as well as diminished IL-4, IL-5, IL-13 and IL-6." (PMID 32900903, 2020). "Animal models are useful and can closely mimic clinical features of asthma, mainly airway hyperreactivity (AHR), which relies on T-helper 2 (Th2) cytokine secretion; interleukin (IL)-5 promotes eosinophil recruitment to the lungs, while IL-13 induces goblet cell hyperplasia and mucus production." (PMID 32778730, 2020). "In reality, we need to know that (for example) an IL5 endotype is driving the child’s asthma before prescribing an anti-IL5 strategy, but this is not practical in current clinical practice." (PMID 32344781, 2020). "Here, we have analyzed the levels of cytokines such as IL-13, IFN-γ, TNF-α, IL-4, IL-5, and IL-1β and growth factors such as HGF, VEGF, and CSF2 or GM-CSF along with the estimation of serum S1P concentration in asthma patients compared with the healthy controls." (PMID 32637407, 2020). "This demonstrates that initiating treatment of T2 inflammation with anti-IL5 or an agent which blocks IL4 and IL13 for subjects with asthma and/or atopic dermatitis who also have CSU, CSU symptoms may be improved." (PMID 32944029, 2020). "In another study, SIRT1 activator (SIRT1720) treatment decreased the eosinophil count and IL-5 and Il-13 levels, but not IL-4 levels in the bronchoalveolar fluid and lung tissue in the ovalbumin-induced asthma mouse model." (PMID 32823491, 2020). "Our results display that both T cells and ILCs seem to contribute to the production of IL-5 and IL-13 when OVA in alum induced asthma, suggesting both immune response pathways of Th2 cells and ILCs can be therapeutic targets for preventing or treating asthma." (PMID 33374657, 2020). "While they reported that serum SIRT1 levels were increased in OVA-sensitized and challenged mice model, SIRT1 levels were decreased in lung tissue, and more IL-4, IL-5, and IL-13 in BALF were found in the ovalbumin-induced asthma mouse model compared to the controls." (PMID 32823491, 2020). "Early studies in patients with mild asthma have shown that CD4+ T cells favour Th2 type immune responses in BALF, lung tissue, and blood, and secrete large amounts of cytokines, such as IL‐4, IL‐5, IL‐13 and IL‐9, while Th1‐type cytokines such as IFN‐γ, IL‐2 and IL‐12 are reduced." (PMID 33124760, 2020). "The level of IL-5 in BALF was significantly higher in OVA-induced asthma model group than in the non-induced group." (PMID 30991656, 2019). "In addition, we evaluated the mechanisms through which MSCs exerted an anti-IL-5 effect and attempted to understand the potential of MSC therapy in children with asthma." (PMID 31673233, 2019). "Regarding the pathological similarity between asthma and AD, the role of HIF-1α and cytokines, especially IL-5 in particular, may give an answer to the unrevealed mechanism of obesity-AD comorbidity." (PMID 31920651, 2019). "We assessed the effect of placenta-derived MSCs on T cell immune responses and cytokine IL-5 levels according to cultures in children with and without asthma." (PMID 31673233, 2019).